PRIMA1 (proline rich membrane anchor 1)
Diseases named in the same sentence as PRIMA1 in open-access papers (continued):
Sharing a sentence is not in itself a finding about the gene and the disease.
cancer (20 papers, 2011 to 2023). A tumor composed of atypical neoplastic, often pleomorphic cells that invade other tissues. "The results showed that PRIMA-1 (APR-017), which covalently binds to the thiols of several polypeptides, and APR-246 (PRIMA-1 Met), a structural analog of PRIMA-1, were sensitive to ARIDIA-deficient cancers." (PMID 34502181, 2021). "Because TP73 was reported to be commonly silenced by promoter hypermethylation in cancers, we proceeded to check if the p73 up-regulation by PRIMA-1 was mediated by demethylation." (PMID 27533450, 2016). "In cancer disease, PRIMA-1 and APR-246 may induce cell death through autophagy in breast cancer and sarcoma cells." (PMID 29258181, 2017). "When validated by PCR, important cancer-related genes such as NOXA (apoptotic gene), GADD34 (cell cycle regulator) and HSPA1A, HSPA1B (encoding HSP70 proteins) were up-regulated by at least two folds upon PRIMA-1 treatment." (PMID 27533450, 2016). "Collectively our data suggest that PRIMA-1 is not useful in reversing downregulation of IGFBP-3 induced by DNA-damaging agents in order to restore an IGFBP-3-induced apoptotic response of cancer cells to these drugs." (PMID 26378048, 2015).
mental disorders (1 paper, 2016). A disease that has its basis in the disruption of mental process. "Increased methylation of PRIMA1 results in decreased enzyme function and increased cholinergic transmission, consistent with a role of the cholinergic circuit in different psychiatric disorders." (PMID 26742039, 2016). "In our study, we investigated the methylation levels of the promoter region and 5′ETS of the ribosomal RNA genes and of the promoter of PRIMA1 in peripheral blood from female patients diagnosed with BPD and age matched control samples from female students without prior history of mental disorders." (PMID 26742039, 2016).
PRIMA1 also shares sentences with these, for which no sentence is quoted: Borderline personality disorder (2 papers); colorectal adenoma (2); acute myeloid leukemia (1); bipolar disorder (1); bladder cancer (1); Esophageal carcinoma (1); hepatocellular carcinoma (1); major depressive disorder (1); multiple myeloma (1); myelodysplastic syndrome (1); myeloproliferative neoplasm (1); schizophrenia (1).